MEG3 (maternally expressed 3)
Diseases named in the same sentence as MEG3 in open-access papers (continued):
Sharing a sentence is not in itself a finding about the gene and the disease.
Alzheimer disease (15 papers, 2019 to 2025). A progressive, neurodegenerative disease characterized by loss of function and death of nerve cells in several areas of the brain leading to loss of cognitive function such as memory and language. "Additionally, an mutant MEFs display upregulation of long noncoding RNA, Meg3, which has been implicated in necroptosis in Alzheimer’s disease." (PMID 39312574, 2024). "This study highlights that lncRNA MEG3 may serve as a potential marker for mitigating hyperglycemia-induced neurotoxicity and associated pathologies, reflecting the microenvironment observed in Alzheimer’s disease." (PMID 40869265, 2025). "Maternally expressed gene 3 (MEG3), located on chromosome 14q32.3 in humans, encodes for a lncRNA of ~1700 bp and has been found to play important roles in the mediation of neuroinflammation in Alzheimer’s disease via its effects on microglia and astrocytes, amongst other functions." (PMID 37569871, 2023). "A previous study reported that icariin (ICA) alleviated Alzheimer’s disease pathology by regulating the expression of MEG3 and MALAT1 lncRNAs and modulating the AKT/GSK3β signaling pathway." (PMID 40869265, 2025). "MEG3, a significant lncRNA involved in the PI3K/Akt pathway, has been associated with Alzheimer disease, epilepsy, diabetic retinopathy, and light-induced retinal degeneration." (PMID 40450528, 2025). "The lncRNA, MEG3, which regulates the insulin signaling pathway implicated in the molecular mechanism of T3D, may be a molecular therapeutic target for managing the onset of complications and the advancement of the disease brought on by diabetes and Alzheimer’s disease." (PMID 40869265, 2025). "Upregulation of Meg3 improves spatial learning and memory ability in rats with Alzheimer's disease via inhibiting the pathological injury of hippocampal neurons." (PMID 36942475, 2023). "A study using an Alzheimer's disease rat model reported that upregulation of MEG3 improved cognitive impairment and alleviates neuronal damage through inactivating the PI3K/Akt signaling pathway." (PMID 35664469, 2022). "In Alzheimer’s disease rat model, up-regulation of lncRNA MEG3 can inhibit the activation of astrocytes in hippocampus in Alzheimer’s disease by inhibiting PI3K/Akt signaling pathway, alleviate neuronal damage, and improve cognitive impairment." (PMID 34093168, 2021). "For example, up-regulating MEG3 ameliorates cognitive impairment, attenuates neuronal damage and abates astrocyte activation in Alzheimer's disease (AD) rat hippocampal tissues by choking the PI3K/Akt pathway." (PMID 34609952, 2021). "Yi and colleagues reported that MEG3 expression is down‐regulated in the hippocampus tissues of rats with Alzheimer's disease (AD), and its up‐regulation can alleviate neuronal damage and improve the functional recovery via the PI3K/AKT signalling pathway." (PMID 32436312, 2020). "This study investigated the regulatory role of the long non-coding RNA maternally expressed gene 3 (MEG3) in tau hyperphosphorylation and insulin signaling (PI3K/AKT1/GSK3β) under high-glucose (HG)-induced neurotoxic conditions mimicking Alzheimer’s disease pathology." (PMID 40869265, 2025). "MEG3 (ENST00000398461)/hsa-let-7d-5p/ATF6B axis showed importance in Parkinson’s and late Alzheimer’s diseases, while AC092687.3/hsa-let-7e-5p/[SREBF2, FNIP1, PMAIP1] and SDCBP2-AS1 (ENST00000446423)/hsa-miR-101-3p/MAPK6 axes are probably related to Alzheimer’s disease development and pathology." (PMID 38027526, 2023). "MEG3 and NEAT1 are related with Alzheimer’s disease and are involved in cognitive decline." (PMID 36710930, 2022). "In addition, dysregulated lncRNAs were also found in neurodegenerative diseases in human, such as lncRNA BACE1-AS and BC200 (Alzheimer’s disease, AD), PINK1-AS (Parkinson’s disease), NEAT1 and MEG3 (Huntington’s disease), AS C9ORF72 (amyotrophic lateral sclerosis) and so on." (PMID 31316349, 2019).
liver fibrosis (15 papers, 2018 to 2024). "The results show the important diagnostic value of serum lncRNA MEG3 in patients with chronic hepatitis B combined with liver fibrosis." (PMID 34899344, 2021). "MEG3 expression levels were significantly decreased in both human fibrotic livers and CCl4-induced mouse liver fibrosis models." (PMID 32098245, 2020). "In human patients experiencing liver fibrosis and cirrhosis, liver MEG3 levels increased significantly." (PMID 30931332, 2019). "The importance of MEG3 in the progression of liver fibrosis makes the gene a potential treatment target." (PMID 30931332, 2019). "Restoring of MEG3 expression led to the suppression of liver fibrosis, with a reduction in α-SMA and type I collagen." (PMID 30282972, 2018). "In conclusion, we demonstrate that MEG3 inhibits Hh-mediated EMT process in liver fibrosis via SMO protein and miR-212." (PMID 30282972, 2018). "Taken together, our results suggest an antifibrotic role of MEG3 in liver fibrosis and this is a first report to show MEG3-mediated EMT process in liver fibrosis via SMO protein." (PMID 30282972, 2018). "In contrast to these results, hepatic MEG3 levels were significantly increased in liver fibrosis and NASH cirrhosis in human patients." (PMID 30134610, 2018). "We demonstrate that MEG3 inhibits liver fibrosis, at least in part, via suppressing Hh-mediated EMT process." (PMID 30282972, 2018). "The inverse relationship between MEG3 and TGFβ1 further suggested the protective effect of MEG3 could extend to hepatic fibrosis in which MEG3 suppressed αSMA expression by indirectly antagonising TGFβ1." (PMID 39872125, 2024). "In conclusion, these findings demonstrate that MEG3 may play an important role in stellate cell activation and liver fibrosis progression and presents as a new potential treatment target for liver fibrosis." (PMID 34899344, 2021). "Finally, they focused on the possibility of lncRNA MEG3 levels as a differentiating marker in chronic hepatitis B types with different degrees of liver fibrosis." (PMID 34899344, 2021). "LncRNA maternally expressed gene 3 (lncRNA MEG3) was found to be down-regulated in both an experimental carbon tetrachloride (CCl4)-induced model of liver fibrosis and fibrotic patients; overexpression of MEG3 decreased HSC activation by suppressing ECM protein synthesis." (PMID 30287731, 2018). "Importantly, the feasibility of using liver MEG3 as a biomarker for patients with liver fibrosis was also investigated." (PMID 30282972, 2018). "Our results suggest an anti-fibrotic role of MEG3 in liver fibrosis." (PMID 30282972, 2018). "Adenoviral vectors expressing MEG3 (Ad-MEG3) was constructed and transferred into CCl4-mice to explore whether MEG3 has an antifibrotic role in liver fibrosis." (PMID 30282972, 2018). "Previous studies from our laboratory also have proved that MEG3 may play an important role in hepatic stellate cell activation and liver fibrosis progression." (PMID 29692724, 2018). "Notably, our results showed that restoring of MEG3 contributed to the suppression of liver fibrosis both in vitro and in vivo." (PMID 30282972, 2018). "Interestingly, MEG3 was also reduced in chronic hepatitis B (CHB) patients with liver fibrosis when compared with healthy controls." (PMID 30282972, 2018). "In this study, MEG3 was reduced in vivo and in vitro during liver fibrosis." (PMID 30282972, 2018). "Our results further confirm an inhibitory role of MEG3 in liver fibrosis." (PMID 30282972, 2018). "Our data suggest that activation of Hh pathway was inhibited by MEG3 in liver fibrosis." (PMID 30282972, 2018). "The inhibitory role of MEG3 was also found in liver fibrosis." (PMID 30282972, 2018).
liver fibrosis (continued). "The most widely studied epigenetic modification, DNA methylation and its relevance to the pathogenesis of liver fibrosis have been well established experimentally, and previous studies have suggested a role for DNA methylation in the deletion of MEG3 expression in tumors." (PMID 34899344, 2021). "Finally, we sought to determine whether aberrantly expressed MEG3 is present in chronic hepatitis B (CHB) patients with liver fibrosis." (PMID 30282972, 2018). "We next analyzed whether they are involved in the effects of MEG3 on liver fibrosis." (PMID 30282972, 2018). "However, the understanding of the role of MEG3 in liver fibrosis remains limited." (PMID 30282972, 2018). "Our results indicate that MEG3 may be a potential biomarker in liver fibrosis." (PMID 30282972, 2018). "Several lncRNAs, including MEG3, GAS5, Gm5091, NR_002155.1, and HIF1A-AS1, have been demonstrated to inhibit liver fibrosis." (PMID 32098245, 2020). "MEG3 and GAS5 can inhibit liver fibrosis, while TUG1 can protect liver grafts during cold preservation." (PMID 31828106, 2019). "We demonstrate that MEG3 inhibits Hh-mediated EMT, at least in part, through interacting with SMO, which is a novel mechanism in regulation of liver fibrosis." (PMID 30282972, 2018). "However, the biological role of MEG3 in liver fibrosis is largely unknown." (PMID 30282972, 2018). "Although several LncRNAs that could affect hepatic fibrosis were already reported including lnc LFAR1, p21, MALAT1, MEG3 and so on." (PMID 32943114, 2020). "Previous investigations demonstrated that overexpression of lncRNAs such as H19, maternally expressed gene 3 (MEG3), growth arrest-specific transcript 5 (GAS5), Gm5091, NR_002155.1, and HIF 1alpha-antisense RNA 1 (HIF1A-AS1) can inhibit the progression of liver fibrosis." (PMID 32098245, 2020). "There was additionally a negative correlation between MEG3 level and α-SMA expression, suggesting liver MEG3 may be a useful biomarker for monitoring liver fibrosis progression in CHB patients." (PMID 30282972, 2018).
pancreatic cancer (15 papers, 2016 to 2024). "This LincRNA gene, MEG3, was closely involved in modulating drug resistance to chemotherapy in multiple types of human cancers including pancreatic cancer." (PMID 34055623, 2021). "MEG3 is another down-regulated lncRNA in pancreatic cancer cells, the expression of which has been inversely correlated with the expression of PI3K." (PMID 34827663, 2021). "The expression levels of MEG3 in both pancreatic cancer tissues and cells were found to be much lower than that in normal tissues and cells." (PMID 34439315, 2021). "Knockdown of MEG3 promoted pancreatic cancer cell proliferation, migration, and invasion while overexpression of MEG3 suppressed pancreatic neuroendocrine tumor cell viability, invasion, and migration." (PMID 34439315, 2021). "Some other studies used other experimental methods on bulk tissues including qPCR and gene edition on cancer cell lines revealed a suppressing effect of MEG3 on human pancreatic cancer." (PMID 34055623, 2021). "Previous survival analyses performed on pancreatic cancer patients revealed that patients with low MEG3 expression had a worse prognosis." (PMID 34827663, 2021). "In clinical samples, expression of MEG3 has been inversely correlated with tumor dimension, organ metastasis, and vascular invasion in pancreatic cancer." (PMID 34827663, 2021). "In pancreatic cancer cells, lncRNA MEG3 was found to be down-regulated." (PMID 36874093, 2023). "The expression of MEG3 has been shown to be negatively correlated with tumor metastasis and vascular invasion in pancreatic cancer Similarly, lncRNA Gas5 was found to inhibit metastasis of pancreatic cancer by regulating the miR-32-5p/PTEN pathway." (PMID 36874093, 2023). "MEG3 is another tumor suppressive lncRNA in cancers including pancreatic cancer." (PMID 34439315, 2021). "In addition, we confirmed the reduced expression of LINC00261 and MEG3, which are thought to function as tumour-suppressive lincRNAs in pancreatic cancer, and especially in neuroendocrine neoplasms in the case of MEG3." (PMID 32727085, 2020). "In addition, 8 paired fresh pancreatic cancer specimens showed decreased MEG3 expressions in PDAC tissues compared with adjacent normal tissues, and 7 of the 8 differences were statistically different." (PMID 33299646, 2020). "For example, we found MEG3 to be downregulated as reported in previous pancreatic cancer studies." (PMID 32727085, 2020). "Therefore, MEG3 affects multiple cellular signaling in pancreatic cancer." (PMID 34439315, 2021). "In addition, MEG3 could also exert its anti-cancer effects on pancreatic cancer by regulation of the PI3K/AKT signaling pathway." (PMID 34439315, 2021). "The association between the absence of MEG3 and poor prognosis was observed in pancreatic cancers." (PMID 30560474, 2019). "We also identified that the low expression of MEG3, LINC01963, and LINC00261 and the high expression of MACC1-AS1, LINC00462, LINC01559, and UCA1 were significantly correlated with worse survival in pancreatic cancer patients." (PMID 34827663, 2021).
pancreatic cancer (continued). "Bulk levels of MEG3 expression were negatively correlated with PI3K expression and were closely correlated with tumor size, metastasis and vascular invasion in pancreatic cancer." (PMID 34055623, 2021). "RUNX1-IT1, ENSG00000254041.1, MALAT1, LOC285194, LncRNA-UFC1, RP11-263F15.1, BC008363, MEG3, and HULC are among lncRNAs whose expressions have been correlated with the survival of patients with pancreatic cancer." (PMID 34827663, 2021). "Reduced MEG3 levels played a crucial role in the PDAC malignant phenotype, which provided insight into novel and effective molecular targets of MEG3 for pancreatic cancer treatment." (PMID 33299646, 2020). "Total expression of MEG3 was not statistically correlated to either histological grade or tumor node metastasis stage in the 25 cases of micro-dissected pancreatic cancer tissues, which we proposed was due to the unpurified cell they used." (PMID 34055623, 2021).
endometrial cancer (14 papers, 2014 to 2025). Primary or metastatic malignant neoplasm involving the endometrium (mucous membrane that lines the endometrial cavity). "MEG3 was reported to be downregulated in highly invasive, sphere-forming, and TX-resistant endometrial cancer cell derivatives." (PMID 40242248, 2025). "Another study supported these findings by demonstrating that MEG3 expression was substantially lower in endometrial cancer samples compared to that in normal endometrial tissues." (PMID 40242248, 2025). "In endometrial cancer cells, MEG3 regulates the PI3K/m-TOR signaling pathway to regulate cell cycle progression, thus regulating apoptosis." (PMID 36523500, 2022). "The overexpression of MEG3 inhibits endometrial cancer cell proliferation, invasion and metastasis via the PI3K pathway." (PMID 32436312, 2020). "Furthermore, MEG3 played a role in modulating PD-L1 expression in aggressive endometrial cancer cells; its expression was regulated by miR-216a." (PMID 40242248, 2025). "In addition, MEG3 inhibited the tumorigenesis and progression of endometrial cancer by repressing the Notch signaling pathway." (PMID 40242248, 2025). "Other studies have shown that the expression of MEG3 and FER1L4 were decreased in EC, and high expression of MEG3 and FER1L4 inhibited the proliferation, migration and invasion of endometrial cancer cells." (PMID 32587476, 2020). "LncRNAs that play a role in tumor suppression in endometrial cancer include: FER1L4, GAS5, MEG3, RP11-395G23.3, LA16C −313D11.11, Xist, Linc ROR, MALAT1, HOTAIR, OVAL, SRA, etc., However, the mechanism of cuproptosis-associated LncRNAs in endometrial cancer is still unclear." (PMID 37124623, 2023). "In addition, MEG3 expression was substantially reduced in endometrial cancer tissues compared to that in adjacent normal tissues and normal endometrial cell lines, such as HEC-1A and KLE." (PMID 40242248, 2025). "In endometrial carcinoma, a distinct regulatory pattern was observed, with LINC00582, LINC-ROR, MEG3, NEAT1, and SNHG12 displaying significant negative correlations." (PMID 41303609, 2025).